EPO (erythropoietin)
Diseases named in the same sentence as EPO in open-access papers (continued):
Sharing a sentence is not in itself a finding about the gene and the disease.
Cerebral ischemia (continued). "Many mechanisms are involved in the function of EPO after brain ischemia or CIRI." (PMID 28848617, 2017). "The antiapoptotic role of EPO was also reported in a rat model of cerebral ischemia, where systemic administration of EPO after middle-cerebral artery occlusion dramatically reduced the volume of brain infarction and promoted cell survival by protecting neurons against hypoxia-induced cell death." (PMID 27504455, 2016). "Enhanced expression of BDNF, EGF, EPO, and bNGF after cerebral ischemia or traumatic brain injuries may contribute to the activation of neurogenesis in the SVZ." (PMID 27832087, 2016). "The findings indicate that FA has certain protective effects on the nerve injury of cerebral ischemia, and suggest that promoting EPO in the brain and peripheral blood may be one of the neuroprotective mechanisms of FA." (PMID 25667662, 2015). "The findings indicate that FA has certain protective effects against the nerve injury induced by cerebral ischemia, and suggest that the promotion of EPO expression in the ischemic brain and peripheral blood may be one of the neuroprotective mechanisms of FA." (PMID 25667662, 2015). "However, exogenous recombinant human erythropoietin was proved to be beneficial in treating global and focal cerebral ischemia and reducing nervous system inflammation in experimental animals." (PMID 25136634, 2014). "Similarly, in animal models, exogenous recombinant human erythropoietin was proved to be beneficial in treating global and focal cerebral ischemia and reducing nervous system inflammation in experimental animals." (PMID 25136634, 2014). "After cerebral ischemia, EPO increase was delayed which is due to de novo synthesis of EPO." (PMID 24490083, 2013). "This suggests that EPO enhances recovery of transmission that is lost during brain ischemia." (PMID 23497299, 2013). "Indeed, EpoR in microvascular/capillary endothelial cells is induced during evolution of cerebral infarct following permanent cerebral ischemia in mice and is further enhanced with EPO treatment." (PMID 22567318, 2012). "EPO also contributes to hypoxic post-conditioning in a mouse model of cerebral ischemia." (PMID 22567318, 2012). "In in-vivo models of cerebral ischemia EPO and its receptor are highly expressed." (PMID 22672319, 2012). "In addition to that, up to 12 h window for Neuro-EPO IN administration as a candidate for neuroprotection in acute brain ischemia is very positive quality." (PMID 22701364, 2012). "Indeed, up to 12 h after brain ischemia is very positive Neuro-EPO administration by the nasal route as a candidate for neuroprotection." (PMID 22701364, 2012). "A few studies have examined the effect of EPO on oligodendrocytes after cerebral ischemia." (PMID 20552017, 2010). "In all, we selected 4 of the 11 groups (each treatment started at one day after cerebral ischemia) for this study: 1) a low-dose combination of EPO (2500 U/kg) + G-CSF (50 μg/kg) (Group I), 2) G-CSF alone (50 μg/kg) (Group C), 3) EPO alone (5000 U/kg) (Group D), and 4) a saline control." (PMID 20404921, 2010). "Seven days after cerebral ischemia, infarct volume was significantly reduced from an average of 159±32 mm3 in saline-treated controls to 77±26 mm3 in EPO, 71±26 mm3 in G-CSF, and 42±23 mm3 in EPO+G-CSF group." (PMID 20404921, 2010). "The objective of this work was to determine the neuroprotective effect of intranasal Neuro-EPO in comparison with the human recombinant EPO injected intraperitoneally in the acute phase of cerebral ischemia, employing the common carotid artery occlusion model in gerbils." (PMID 21103798, 2010). "Apart from enhancing the endogenous production level of EPO, the administration of exogenous rhEPO has been demonstrated to reduce ischemic brain injury and improve functional recovery both at the acute and late stages of cerebral ischemia in the pre-clinical and clinical studies." (PMID 35250554, 2022).
Cerebral ischemia (continued). "Furthermore, in an experimental model of cerebral ischemia, it was shown that the protective effects of erythropoietin (EPO), which is capable of reducing BBB disruption and neuronal death, depend on a mechanism involving Cx43 phosphorylation, although the level of Cx43 was not modulated." (PMID 36076908, 2022). "Taken together, our results suggest that EPO treatment improves white matter integrity after cerebral ischemia, which could be attributed to EPO attenuating gliosis and facilitating the microglial polarization toward the beneficial M2 phenotype to promote oligodendrogenesis." (PMID 28840056, 2017). "Among them vascular endothelial growth factor (VEGF) and erythropoietin (Epo) originally identified as master regulators of angiogenesis and erythropoiesis, respectively, have also been shown to promote neuronal survival upon cerebral ischemia through induction of anti-apoptotic pathways." (PMID 24409307, 2014). "In a previous report, we have demonstrated that intranasal (IN) administration of Neuro-EPO proved to be safe, reaches the brain in few minutes, does not stimulate erythropoiesis after acute treatments, and shows efficacy in some rodent models of brain ischemia." (PMID 22701364, 2012). "Tissue hypoxia and cerebral ischemia activate HIF-1α, which in turn activates transcription of the EPO and Vascular Endothelial Growth Factor (VEGF) genes." (PMID 38302546, 2024). "Further study demonstrated that a mutant EPO (MEPO) shifted microglia toward M2 polarization by promoting JAK2/STAT3 activation and inhibiting the expression of C/EBPβ at 14 days after cerebral ischemia-reperfusion in middle-aged (9-month-old) mice." (PMID 35250554, 2022). "Up regulation of vascular endothelial growth factor (VEGF) or erythropoietin (EPO) promotes adaptation to hypoxic/ischemic stress and results in reduced infarct size after cerebral ischemia in MCAO model in rodents." (PMID 34439764, 2021). "In hypoxic preconditioning when mild brain ischemia protects against severe ischemic challenge, HIF activation increases VEGF and EPO expression to promote tolerance to brain ischemia." (PMID 22567318, 2012). "At one week after cerebral ischemia, CBF was significantly greater in the ischemic cortex of the EPO+G-CSF-treated rats than that in EPO, G-CSF or control (each group n = 8)." (PMID 20404921, 2010). "Erythropoietin (EPO) and erythropoietin receptor (EPOR) system demonstrated to have a key role during central nervous system embryogenesis, have increased expression during cerebral ischemia, and are still expressed in adult brain." (PMID 24490083, 2013). "EPO was administered via a transcranial route in prior studies of brain ischemia because EPO does not cross the blood-brain barrier (BBB)." (PMID 21766022, 2011). "We then evaluated the interaction among EPO, VEGF and Src proteins in promoting angiogenesis by performing glucose-oxygen deprivation/reoxygenation (OGD/R) experiments on brain microvascular endothelial bEnd.3 cells to simulate cerebral ischemia/reperfusion injury (CIRI)." (PMID 36108080, 2022). "Likewise, it was shown that Hpc-bone marrow MSCs (BM-MSCs) enhanced the angiogenesis and neurogenesis in cerebral ischemia rat model through upregulation of growth factors including BDNF, GDNF, VEGF, and erythropoietin with downregulation of inflammatory cytokines." (PMID 33381188, 2020). "EPO stimulation of improved oxygen delivery may also contribute to protective action in other non-hematopoietic tissue such as brain ischemia and skeletal muscle injury." (PMID 32038269, 2019).
Cerebral ischemia (continued). "We conclude that although post-ischemic treatment with EPO is not neuroprotective in a model of cardiac arrest brain ischemia, its markedly positive effect on brain plasticity and recovery of memory function warrants consideration as treatment of cardiac arrest patients." (PMID 23497299, 2013).
end-stage renal disease (63 papers, 2005 to 2025). "Their study suggests that a genetically determined ability of EPO synthesis predisposes diabetic patients to the development of diabetic proliferative retinopathy and end-stage renal failure." (PMID 24782919, 2014).
heart failure (63 papers, 2008 to 2025). Inability of the heart to pump blood at an adequate rate to meet tissue metabolic requirements. "We examined how endogenous EPO activity contributed to the regulation of heart failure-associated gene expression by comparing expression in WT and ΔEPORE male mice." (PMID 38628440, 2024). "ΔEPORE mice had increased expression of heart failure-associated genes, hypertrophic cardiomyopathy-related genes, and sarcomeric genes that were also elevated with EPO treatment in WT mice." (PMID 38628440, 2024). "High-dose EPO also increased heart failure-associated genes such as Cdk8, Nox4, S100A, and SERCA2a, and hypertrophic cardiomyopathy-related genes such as Acta1, Myh7, Nppa, and Nppb in male WT mice but not in ΔEPORE male mice." (PMID 38628440, 2024). "Several studies have linked protein carbamylation with adverse outcomes — including erythropoietin resistance, heart failure, and mortality in ESRD — and increased risk of CKD progression in a pilot study of 150 participants from the CRIC Study." (PMID 36048534, 2022). "The etiology of anemia associated with heart failure is not fully understood, but current data suggest the involvement of multiple mechanisms: iron deficiency, inflammation, low erythropoietin levels, hemodilution, and bone marrow dysfunction." (PMID 31269687, 2019). "The decreased renal perfusion in heart failure patients causes renal hypoxia and enables the release of erythropoietin (EPO), but the response of the bone marrow to EPO is blunted due to the proinflammatory cytokines." (PMID 25710019, 2015). "Erythropoietin secretion is reduced because of renal hypoxia, causing a further reduction in haemoglobin concentration, which exacerbates cardiac failure." (PMID 21655315, 2011). "With EPO administration, in contrast to the protective effect to the cardiac injury of acute EPO treatment, extended EPO treatment to increase hematocrit in WT mice adversely affected the heart function with a corresponding increase in expression of heart failure-associated genes." (PMID 38628440, 2024). "In heart failure, chronic inflammation represents an important cause of erythropoietin resistance." (PMID 37374094, 2023). "By acting at the transcriptional level, PHIs maintain endogenous EPO levels within the physiological range preventing sudden and/or excessive Hgb level elevations potentially reducing the risk of cardiovascular events, thromboembolism and heart failure compared with current treatments." (PMID 36048866, 2023). "Medical management of heart failure and hemolytic anemia with red blood cell transfusion, erythropoietin, intravenous iron, or folic acid is of limited value." (PMID 40364865, 2025). "The post hoc analyses of randomized trials have revealed an elevation in the erythropoietin level, a decrease in hepcidin, and myocardial iron repletion following empagliflozin treatment in patients with heart failure." (PMID 38592232, 2024). "Investigated the use of erythropoietin-stimulating agents in anaemic patients with heart failure, discussing benefits and challenges." (PMID 39184703, 2024). "RhEPO also has additional safety concerns such as increased risk of venous thromboembolism, stroke, myocardial infarction (MI), heart failure and death owing to the supraphysiological EPO levels leading to sudden and/or excessive haemoglobin (Hgb) levels." (PMID 36048866, 2023). "Previous research has shown that EPO can reduce intracellular ER stress, protecting rats against cardiac failure and nephrotoxicity." (PMID 37697015, 2023). "The improved renal function will, in turn, bring benefits to heart failure via increased EPO generation, etc., thereby creating a virtuous cycle for cardiorenal interaction." (PMID 36186974, 2022). "Though the upgradation of sympathetic and renin angiotensin system increases the production of EPO in kidneys, the drugs used in heart failure commonly blunts this response." (PMID 34453627, 2021).
heart failure (continued). "In fact, studies of EPO levels in patients with heart failure showed that excessive EPO synthesis predicts mortality in chronic and acute heart failure, possibly reflecting a status of advanced cardiac disease." (PMID 33330669, 2020). "In the pathophysiology of heart failure, EPO levels are elevated in response to global tissue hypoxia, but this elevation is not proportional to the detected hemoglobin levels, a mismatch caused by the resistance of hematopoietic bone marrow to EPO." (PMID 31269687, 2019). "This novel combination of injectable hydrogels, iPSCs, and the cardioprotective molecule EPO provides a highly translational strategy with excellent potential for prevention of cardiac failure." (PMID 28988988, 2017). "EPO improves cardiac function and induces neovascularisation in post-myocardial infarction (MI) heart failure." (PMID 27561278, 2016). "It has been shown that higher levels of EPO are accompanied by higher mortality in a number of patients' subgroups (i.e., Patients with heart failure)." (PMID 24575050, 2014). "The therapeutic relevance of EPO in the clinical setting of cardiovascular diseases has been confirmed by studies in which EPO treatment was started 3 or 6 weeks after induction of myocardial infarction, when heart failure was fully established in mice." (PMID 21943500, 2011). "Erythropoietin and thrombomodulin have also been shown to play a role in endothelial function and heart failure." (PMID 18800166, 2008). "There were a total of 6 deaths, including 3 cases in the roxadustat group (1 case of peritonitis, 1 case of cerebral infarction, and 1 case of arrhythmia) and the other 3 cases in the EPO group (1 case of peritonitis, 1 case of gastrointestinal hemorrhage, and 1 case of heart failure)." (PMID 40000368, 2025). "Unlike WT mice, EPO treatment did not increase expression of heart failure-associated gene expression in nNOS−/− mice." (PMID 38628440, 2024). "High erythropoietin levels have been linked to poor clinical outcomes in heart failure, and HIF-PH inhibitors may effectively raise hemoglobin with much lower erythropoietin levels by addressing erythropoietin resistance." (PMID 39768541, 2024). "EPO treatment did not change expression of heart failure-associated gene expression in nNOS−/− mice." (PMID 38628440, 2024). "Notably, the presence of heart failure-related inflammation facilitates erythropoietin resistance and iron metabolism dysfunction." (PMID 39768541, 2024). "Conversely, systemic inflammation—a common feature in heart failure—may reduce erythropoietin production and impair bone marrow erythropoiesis, potentially limiting the efficacy of HIF-PH inhibitors." (PMID 39768541, 2024). "It is indicated that the production of erythropoietin is decreased in patients with heart failure." (PMID 36979925, 2023). "Furthermore, EPO levels predict the mortality rate of patients with heart failure, and consistently elevated EPO levels have independent prognostic value." (PMID 32290638, 2020). "The aim of the current study was to determine whether combining mechanically tailored injectable hydrogels, iPSC therapy, and the cardioprotective molecule EPO could provide a novel strategy to prevent cardiac failure in a rat model of MI." (PMID 28988988, 2017). "Renal impairment is encountered in about 66% of heart failure patients, which may partly contribute to the lower than expected increase of erythropoietin in response to hypoxemia and decreased perfusion." (PMID 23213342, 2012). "Some previous studies showed that in chronic post-myocardial infarction(MI) heart failure models, EPO increased incorporation of EPCs into the myocardial microvasculature and improved neovascularization, which was associated with increased EPOR and VEGF expression in ischemic hearts." (PMID 22954171, 2012).
heart failure (continued). "However, we found that extended EPO treatment to increase hematocrit compromised heart function, while the loss of neuronal NOS (nNOS) was protective against the deleterious activity of EPO to promote heart failure." (PMID 38628440, 2024). "A potential association between elevated EPO and cardioprotection is suggested by increased EPO production and erythropoiesis associated with treatment with sodium-glucose cotransporter 2 (SGLT2) inhibitors for metabolic disorders that are associated with a reduced risk of heart failure events." (PMID 38628440, 2024). "Therefore, according to our results, compared with the normal group, HBB is highly expressed, which may be related to the abnormal activation of sympathetic nervous system and the level of erythropoietin in heart failure." (PMID 35346191, 2022). "However, while EPO treatment increased expression of these heart failure-associated genes in WT mice, EPO treatment did not change expression of heart failure-associated genes Cdk8, TGFβ2, and NOX4 and hypertrophic cardiomyopathy-related genes Nppa in nNOS−/− mice." (PMID 38628440, 2024). "However, such relative EPO deficiency would imply rhEPO use could be beneficial, which has not been the case in clinical studies in heart failure." (PMID 33330669, 2020). "Erythropoietin (EPO) improves cardiac function and induces neovascularisation in post-myocardial infarction heart failure." (PMID 27561278, 2016). "Low erythropoietin production and decreased serum albumin may be related to the mechanism by which RDW affects the prognoses of heart failure patients." (PMID 37206106, 2023).